RBAK (RB associated KRAB zinc finger)
Description:
May repress E2F-dependent transcription. May promote AR-dependent transcription.
Synonyms: ZNF769
Tractability: PROTAC: UniProt records ubiquitination sites on it; ubiquitination databases record sites on it.
Gene: Protein-coding gene on chromosome 7 (5,045,821 to 5,069,491, forward strand). Ensembl gene ENSG00000146587.
Subcellular location: Nucleus
Subcellular location (Human Protein Atlas): Nucleoplasm
Gene Ontology:
Molecular function: protein binding; DNA-binding transcription factor activity, RNA polymerase II-specific; RNA polymerase II cis-regulatory region sequence-specific DNA binding; zinc ion binding
Biological process: negative regulation of DNA-templated transcription; regulation of DNA-templated transcription; regulation of transcription by RNA polymerase II
Cellular component: nucleoplasm; nucleus
Genetic constraint (gnomAD): Loss-of-function variants: 38 observed, 66.52 expected, observed/expected ratio (o/e) 0.57, 90% interval 0.44 to 0.75. The upper end of that interval is the gene's LOEUF score, 0.75, which puts it in group 3 of 6, group 1 being the genes least tolerant of losing a copy. Missense variants: 880 observed, 890.12 expected, observed/expected ratio (o/e) 0.99, 90% interval 0.94 to 1.04. Synonymous variants: 341 observed, 303.09 expected, observed/expected ratio (o/e) 1.13, 90% interval 1.03 to 1.23.
Homologues: Orthologues: chimpanzee RBAK (99% identical), macaque RBAK (97% identical), pig RBAK (89% identical), guinea pig RBAK (84% identical), mouse Rbak (79% identical), rat Rbak (79% identical), rabbit RBAK (61% identical). Paralogues in human: ZNF12 (69% identical), ZNF432 (40% identical), ZNF615 (38% identical), ZNF268 (36% identical), ZNF658 (35% identical), ZNF33B (34% identical), ZNF717 (34% identical), ZNF33A (33% identical), ZNF484 (33% identical), ZNF182 (33% identical), ZNF841 (32% identical), ZNF568 (32% identical), and 164 more.
Diseases named in the same sentence as RBAK in open-access papers:
RBAK is named in the same sentence as 10 diseases in open-access papers, as found by Europe PMC text mining. Sharing a sentence is not in itself a finding about the gene and the disease. The quoted sentences say what the papers report.
prostate carcinoma (4 papers, 2016 to 2024). A carcinoma that arises from epithelial cells of the prostate gland. "RBAK (RB-associated KRAB zinc finger) was reported to be upregulated in NSCLC, cholangiocarcinoma, and prostate cancer, likely due to a decreased level of its upstream negative regulator—miR135a." (PMID 33672287, 2021). "In addition, androgen-induced miR-135 regulates prostate cancer apoptosis through suppression of the RB-associated KRAB zinc finger (RBAK) and limits prostate cancer migration through the downregulation of matrix metalloproteinase 11 (MMP11)." (PMID 39273446, 2024). "In prostate cancer, miR-135a repressed cell migration and proliferation by downregulating matrix metallopeptidase 11 (MMP11), rho associated coiled-coil containing protein kinase 1 (ROCK1), ROCK2, RB associated KRAB zinc finger (RBAK) and STAT643,60,64." (PMID 32944391, 2020). "Furthermore, RBAK was shown to inhibit apoptosis in prostate cancer." (PMID 33672287, 2021). "Next, the expression levels of miR-135a, RBAK and MMP11 were further examined in 10 normal prostate tissues and 13 prostate cancers with real-time PCR." (PMID 27323416, 2016). "To evaluate possible prognostic value of miR-135a, RBAK and MMP11, we analyzed RNAseq data from TCGA, a cohort of 52 normal prostate tissues and 419 prostate cancer samples." (PMID 27323416, 2016). "Meanwhile, we found the mRNA levels of RBAK and MMP11 significantly increased (P < 0.001) in metastatic prostate cancers and local prostate cancers compared to normal prostate tissues by analyzing GSE6919 database." (PMID 27323416, 2016). "We found that miR-135a was downregulated and RBAK was upregulated in prostate cancer samples compared with normal prostate tissues." (PMID 27323416, 2016). "We then evaluated miR-135a, RBAK and MMP11 expression level in the noncancerous prostatic cells WPMY-1 and four prostate cancer cell lines LNCaP, 22Rv1, DU145 and PC-3." (PMID 27323416, 2016).
lung carcinoma (1 paper, 2021). "Together with the in vitro data demonstrating that RBAK-silenced lung cancer cells have lower migration and invasion capacity, these results implicate RBAK association with the progression of metastases in NSCLC." (PMID 33672287, 2021).
lymphoma (1 paper, 2022). A malignant (clonal) proliferation of B- lymphocytes or T- lymphocytes which involves the lymph nodes, bone marrow and/or extranodal sites. "RBAK was computationally predicted as a downstream target of miR‐155 in lymphoma, although the function of RBAK in solid tumours remains poorly understood." (PMID 35735060, 2022).
melanoma (1 paper, 2024). A malignant, usually aggressive tumor composed of atypical, neoplastic melanocytes. "The TWAS detected 27 genes associated with melanoma with p-values less than 0.05 (the top three genes are LOC389458 (RBAK), C16orf73 (MEIOB), and EIF3CL)." (PMID 39061157, 2024).
ovarian carcinoma (1 paper, 2022). A malignant neoplasm originating from the surface ovarian epithelium. "Our analysis revealed differential regulation of RBAK and RB1 in patients, which implies the importance of interactions between these two genes in ovarian cancer and their potential as drug targets." (PMID 35735060, 2022).
prostate tumors (1 paper, 2016). "To determine the role of miR-135a and its targets in the pathogenesis of PCa, we investigated miR-135a, RBAK and MMP11 expression levels in prostate tumors compared to normal prostate tissues using two publicly available gene expression database: GSE21036 and GSE6919." (PMID 27323416, 2016).
tumor (5 papers, 2012 to 2023). "A previously reported model indicated that RB1 functions as an essential tumour suppressor, which physically interacts with RBAK." (PMID 35735060, 2022). "Our study highlights miR-135a was an androgen-induced tumor suppressor that might be downregulated by androgen depletion, thus up-regulating RBAK and MMP11 promote PCa progression." (PMID 27323416, 2016). "In the present study, we demonstrated that as an androgen-induced tumor suppressor, miR-135a decreased PCa cells proliferation and induced PCa cell cycle arrest and apoptosis through its target RBAK, and repressed cell migration by down-regulating the expression of MMP11." (PMID 27323416, 2016). "Among these genes, BRCA1, RB1, RBAK and CSMD3 are tumour suppressors, while TRRAP functions as an oncogene." (PMID 35735060, 2022). "A limitation of our analysis is that we did not screen the tumor DNA for gene mutations or ascertain gene expression levels; nevertheless, we found that RB1 and RBAK are differentially methylated between the papillary serous and normal fallopian tube samples." (PMID 22403726, 2012).
cancer (3 papers, 2015 to 2021). A tumor composed of atypical neoplastic, often pleomorphic cells that invade other tissues. "Since fibroblasts in the stroma of desmoplastic cancers provide optimal microenvironment for CCA progression and they usually become susceptible for apoptosis, it would therefore be possible that overexpression of serum RBAK in CCA patients may be from apoptogenic cancer-associated fibroblasts." (PMID 26060332, 2015).
RBAK also shares sentences with these, for which no sentence is quoted: cholangiocarcinoma (1 paper); metastatic prostate carcinoma (1).